EGF (epidermal growth factor)
Diseases named in the same sentence as EGF in open-access papers (continued):
Sharing a sentence is not in itself a finding about the gene and the disease.
acute kidney injury (16 papers, 2015 to 2025). Sudden and sustained deterioration of the kidney function characterized by decreased glomerular filtration rate, increased serum creatinine or oliguria. "In the kidney, EGF promotes tubular cell proliferation and has been linked to modulating the recovery from acute kidney injury." (PMID 32280839, 2020). "The healing of acute kidney injury is significantly impacted by both epidermal growth factor (EGF) and insulin-like growth factor (IGF)." (PMID 40426269, 2025). "The major focus was on tubule-specific urinary EGF, which has proven its utility as a surrogate marker of tubular regenerative potential after acute kidney injury." (PMID 40076962, 2025). "High urinary levels of EGF (uEGF) reflect functional tubular mass and regeneration potential and promote tubular cell proliferation modulating the recovery from acute kidney injury." (PMID 38095674, 2024). "Expression levels of NDUFAF1 in two central nodes involved in epidermal growth factor (EGF) and Olfactomedin 4 (OLFM4) have been associated with acute kidney injury and septic shock." (PMID 38783263, 2024). "Exogenous EGF has been shown to enhance renal tubular cell regeneration and accelerate the recovery of the kidney function in a rodent model of acute kidney injury." (PMID 32280839, 2020). "Comparable alterations in the EGF level were observed in patients suffering from acute renal failure." (PMID 30116500, 2018). "Following HgCl2, injection tubular injury scores increased and serum urea nitrogen levels reached uraemia after 3 days, but EGF-treated groups were resistant to this acute kidney injury." (PMID 25389045, 2015). "Exogenous EGF increased the proportion of proximal tubule cells in S-phase, particularly following acute kidney injury." (PMID 25389045, 2015). "Thus, exogenous EGF is effective at promoting recovery from a variety of acute kidney injury, even though a major source of EGF is the kidney itself." (PMID 25389045, 2015). "However, it is unclear whether urinary EGF is a suitable monitoring marker of tubular repair status after acute kidney injury (AKI) in humans." (PMID 38732362, 2024). "Moreover, decreased renal expression and urinary excretion of EGF were found in human kidney diseases such as diabetic nephropathy, immunoglobulin A nephropathy, acute kidney injury and lupus nephritis, and in PKD, and were interpreted as a sign of insufficient repair." (PMID 36914219, 2023). "Following acute kidney injury (AKI), EGF produced by the proximal tubule cells stimulates vascular epidermal growth factor secretion and enhances proliferation of proximal tubule cells, which is important for the recovery from AKI." (PMID 31906817, 2020).
cholangiocarcinoma (16 papers, 2010 to 2026). A carcinoma that arises from the intrahepatic biliary tree (intrahepatic cholangiocarcinoma) or from the junction, or adjacent to the junction, of the right and left hepatic ducts (hilar cholangiocarcinoma). "Pathogenetic studies of clinical samples revealed integrin αvβ3 cross-talked with EGFR and downstream signal transduction networks affected by thyroid hormone and EGF related to the progression of cholangiocarcinoma malignancy." (PMID 41799774, 2026). "It has been already shown that the induction of the EGF/EGFR axis can initiate EMT in cholangiocarcinoma (CCA) cell lines and in the human embryonal rhabdomyosarcoma cell line." (PMID 31671862, 2019). "EGF-mediated FOXO4 phosphorylation in cholangiocarcinoma leads to the transcriptional inhibition of ANXA8, FAK downregulation, and alteration of F-actin kinetics." (PMID 31474227, 2019). "The EGF/EGFR axis triggers EMT in cholangiocarcinoma cells by inducing scatter of cholangiocarcinoma cells, as well as nuclear translocation of β-catenin." (PMID 27050434, 2016). "Cell growth was increased in cholangiocarcinoma following EGF stimulation and this was significantly attenuated by kinase inhibitors." (PMID 20565817, 2010). "For FOXO4, ANXA8 is transcriptionally down-regulated by EGF-mediated FOXO4 phosphorylation, which is correlated with the morphologic changes of EMT in the cholangiocarcinoma cells." (PMID 27976702, 2016). "During the tumorigenesis of cholangiocarcinoma, cholestasis and chronic inflammation may induce bile duct epithelial cells to produce variable cytokines including IL-6, IL-8, TGF-β1, TNF-α, platelet-derived growth factor, and epidermal growth factor." (PMID 30469416, 2018). "EGF, HGF/MET, VEGF, KRAS/MAPK, and IL-6/STAT pathways have been found to be deregulated in cholangiocarcinoma, but no effective therapies targeting these pathways have been developed." (PMID 26475437, 2015).
cognitive decline (16 papers, 2011 to 2025). "Additional studies contribute to the correlation of low plasma EGF levels with low baseline cognitive performance and the risk of cognitive decline in PD patients." (PMID 40405084, 2025). "In rodents, EGF prevented cognitive decline and was associated with a reduction of microhemorrhages but not with changes in Aβ levels." (PMID 37686198, 2023). "Low EGF levels are associated with frontal and temporal lobe-mediated changes in cognitive function and predict cognitive decline." (PMID 36383265, 2023). "EGF prevented cognitive decline and was associated with lower microbleeds and higher CV coverage, but not with changes in Aβ levels." (PMID 27788676, 2016). "In order to select a sex and genotype of EFAD mice for treatment with EGF, it was important to identify the association among cognitive decline and CV dysfunction." (PMID 27788676, 2016). "EGF prevented cognitive decline and was associated with lower microbleeds and higher CV coverage, but not changes in Aβ levels." (PMID 27788676, 2016). "In a study assessing baseline plasma levels of 102 proteins in PD patients, only decrease of epidermal growth factor (EGF) was found to correlate to poor cognitive scores at baseline and predict a major risk of cognitive decline." (PMID 25386162, 2014). "In addition, serum levels of the insulin growth factor 1 (IGF-1) and epidermal growth factor (EGF) are associated with cognitive decline in early stage and drug-naïve patients with PD." (PMID 26566043, 2015). "Other potential biomarkers include low serum levels of uric acid, epidermal growth factor, and insulin-like growth factor that were predictive of cognitive decline in PD, and highly predictive of cognitive decline in PDD." (PMID 37964309, 2023). "As EGF induced a pronounced effect on preventing cognitive decline in E4FADF mice, it is important to consider potential mechanisms of action." (PMID 27788676, 2016). "EGF induced a profound protective effect on cognitive decline in E4FADF mice compared to the vehicle control (VC)." (PMID 27788676, 2016). "In summary, our data demonstrate that EGF prevents cognitive decline in female mice that express APOE4 and overproduce Aβ." (PMID 27788676, 2016). "A study in a murine model overexpressing human APOE4, with increased Aβ1–42 burden and cognitive impairment, lower plasma EGF was also reported, and EGF treatment was shown to alleviate cognitive decline, reduce microbleeds and increase cerebrovascular coverage." (PMID 41373821, 2025). "However, there is evidence that EGF is a biomarker for cognitive decline in PD." (PMID 40405084, 2025). "Importantly, low levels of epidermal growth factor (EGF) may be predictive of cognitive decline." (PMID 34912207, 2021).
colitis (16 papers, 2006 to 2025). Inflammation of the colon. "In contrast to deleterious outcomes of colitis associated with treatment with gefitinib, treatment of animals with EGF during DSS-induced injury improved overall outcomes." (PMID 29904166, 2018). "Considering the similar structure to EGF, we further examined if rSPINK4 rescued colitis by directly interacting with EGFR." (PMID 38997284, 2024). "Parasitic infection during colitis was associated with elevated levels of AREG, EGF, IGFBP-3, and reduced levels of both PDGF-AA and -BB." (PMID 36836678, 2023). "Epidermal growth factor (EGF)-like growth factor amphiregulin, which MCs also secrete, directly boosted the Treg function in colitis and tumor vaccination models by activating the EGF receptor (EGFR) on them." (PMID 36189267, 2022). "We found that administering EGF during the period of maximum colitis severity (“early”), coincident with the initiation and early promotion of tumors, improved outcomes of colitis and reduced tumor size." (PMID 29904166, 2018). "Tumors were smaller when EGF was given during injury/colitis (or early) phase, but larger when EGF was given during the healed/remission (or late) phase." (PMID 29904166, 2018). "A qualitative microscopic examination of the colitis suggested improved surface epithelialization in the colons of EGF-treated animals." (PMID 29904166, 2018). "The researchers found that there was a significant increase of Proliferating Cell Nuclear Antigen (PCNA) and Epidermal Growth Factor (EGF) in the chronic and acute colitis model which was administrated with a dose of 10 mg/kg EC (EC10)." (PMID 28335502, 2017). "Given the critical importance of TNF-α and EGF on intestinal inflammation, mucosal repair, and the development of cancer, the identification of signaling interactions between them may provide invaluable insight in the pathophysiology of colitis-associated cancer." (PMID 23688423, 2013). "Dietary supplementation with NAC can alleviate AA-induced colitis in a porcine model through regulating anti-oxidative responses, cell apoptosis, and EGF gene expression." (PMID 24001404, 2013). "This can explain the reduction in diarrhoea in colitis, which was achieved by administration of EGF enemas in patients suffering from ulcerative colitis." (PMID 16571116, 2006). "An example is epidermal growth factor [EGF], which has been shown to increase cAMP stimulated ENaC mediated sodium transport in the mouse model of colitis." (PMID 16571116, 2006). "Most of these regulatory molecules reduce mucosal damage and intestinal inflammation in in vivo models of colitis, however EGF family peptides (EGF, TGF-α and TGF-β) occupy a central role in the healing mechanisms and therefore will be discussed more extensively." (PMID 24886810, 2014). "It had been indicated that EGF could accelerate ulcer repair in the experimental colitis animal model, resulting in the alteration of downstream signaling cascades and subsequently catalyzing preferential substrates mediated by DAG, IP3 and phosphorylated RAS." (PMID 23825635, 2013). "While the EGF can stimulate epithelial cells to proliferate, the study indicated that EC could induce the proliferation of epithelial cells, to recover the intestinal mucosa of colitis, and reduce the relapse lesion." (PMID 28335502, 2017). "The UC group showed severe colitis, increased TNF‐α and IL‐6, decreased IL‐10, elevated TOC, reduced TAC, altered VEGF/EGF mRNA, PI3K/AKT activation, and increased apoptosis (Bax/Bcl‐2 ratio, Cytochrome c, Caspase‐9, Caspase‐3)." (PMID 40688608, 2025). "In this study, after administering Ento-PB to rats with OXZ-induced colitis, the expression levels of IL-13 and TNF-α significantly decreased, while the expression levels of IL-4, IL-10, and EGF sharply increased." (PMID 39230095, 2024).
colitis (continued). "In our study, we observed a very strong induction of EGF-pathway components during nematode infection, with even higher expressions of AREG and EGF, ligands for EGFR in mice infected with parasites and with induced colitis." (PMID 36836678, 2023). "On the other hand, Nlrx1-deficiency led to increased expression of wound healing factors epidermal growth factor (EGF) and TGFβ in epithelial cells in a mouse model of DSS-induced colitis." (PMID 35651602, 2022). "Early studies have tested targeting epithelial cells, e.g., by activating EGF or TGFβ signaling, to treat colitis, yet, those studies failed to meet the expectation due to the mild efficacy and side effects of the treatments." (PMID 36528592, 2022). "The increase in EGF expression observed in our work may explain the increased cell proliferation observed, and may be one of the mechanisms of action of EC10 against colitis." (PMID 23346204, 2012). "No changes were observed in overall histological colitis score due to EGF treatment (p = 0.99)." (PMID 29904166, 2018).
ischemia (16 papers, 2012 to 2025). A hypoperfusion of the BLOOD through an organ or tissue caused by a PATHOLOGIC CONSTRICTION or obstruction of its BLOOD VESSELS, or an absence of BLOOD CIRCULATION. "EGF is an important regulatory factor of intestinal mucosal homeostasis and has a strong repair effect on intestinal morphological damage caused by weaning, intestinal ischemia/reperfusion, and necrotizing enterocolitis." (PMID 36077965, 2022). "It is also reported that EGF protects neurons in the hippocampus against ischemia-related damage in vivo." (PMID 33953854, 2021). "For example, the level of EGF was found to be decreased following ischemia and restores its basal level during the recovery phase of ischemia/reperfusion injury." (PMID 30116500, 2018). "EGF administration after ischemia at a concentration of 10−8 M resulted in comparable improvement in cardiac parameters compared with Losartan administered at a concentration of 2×10−6 M." (PMID 22720029, 2012). "Acute administration of EGF either before or after ischemia led to marked improvements in cardiac function in the diabetic heart following I/R." (PMID 22720029, 2012). "EGF is an important cell protective peptide, which has certain antioxidant function and can alleviate oxidative injury induced by LPS and intestinal ischemia/reperfusion." (PMID 36077965, 2022). "However, as neuroprotective effects due to anti-oxidative properties were well described for other neurotrophic factors, e.g., the nerve growth factor, EGF probably also counteracts the ischemia-related oxidative stress." (PMID 28445478, 2017). "Indeed, our results showed that combination of Losartan with EGF administration after ischemia significantly improved cardiac recovery more than with each drug alone." (PMID 22720029, 2012). "EGF is a potent proliferative factor for NPCs that strongly promote the mitogenesis of NPCs in vitro, in the normal adult brain, and in brains injured by Aβ, ischemia, and trauma; the differentiation-inducing effect of EGF is weak and exhibits a glial tendency." (PMID 23437202, 2013). "Rescue of ischemia and/or G7 dendrimer-mediated attenuation of cardiac EGFR signaling by exogenous EGF administration would explain the improved recovery from I/R injury, though further study is needed." (PMID 39319862, 2025). "We further investigated the expression patterns of AR, EPR, EGF, BTC, HB-EGF, and TGF-α in the cortex, striatum, and hippocampus via RT-PCR following an in vivo ischemia assay." (PMID 25675253, 2015). "Some factors such as ATP, EGF, and TGF, play an important role in the astrogliosis in vitro and in vivo, however, whether the glial scar induced by such factors in vitro closely mimics that after ischemia remains doubt, since there may exist complex system to induce the glial scar after ischemia." (PMID 22629422, 2012).
leukemia (16 papers, 2012 to 2025). A malignant (clonal) hematologic disorder, involving hematopoietic stem cells and characterized by the presence of primitive or atypical myeloid or lymphoid cells in the bone marrow and the blood. "Recent research showed the ability of an insect extracts (E. sinensis Walker) to inhibit the proliferation of leukemia K562 by inhibiting EGF secreting and blocking the EGFR signaling pathway, suggesting a relevance of EGFR in human hematological diseases." (PMID 26682280, 2015). "The optimal SFM contained a RPMI1640+ epidermal growth factor (20 ng/ml), a basic fibroblast growth factor (20 ng/ml), a leukemia inhibitory factor (20 ng/ml), a B-27 serum-free supplement (20 μl/ml), and a bovine serum albumin (4 μg/ml)." (PMID 24188098, 2013). "First isolated from the T-leukemia cell line J6, FAT1 is located on human chromosome 4q35.2, consists of 27 exons, and encodes proteins with a single transmembrane domain, 34 extracellular cadherin repeats, and laminin G-like and epidermal growth factor (EGF)-like domains." (PMID 35646625, 2022). "Selective inhibition of SphK1 by VPC96091, induces the reduction of epidermal growth factor (EGF), which drives S1P levels and then increases Akt/ERK phosphorylation in human leukemia U937 cells and mice model." (PMID 38419070, 2024). "M-MΦs secrete prosurvival factors, such as HGF, and EGF, and high levels of VCAM-1, which has been demonstrated to play an essential role in the BM stromal compartment in mediating leukemia cell chemoresistance." (PMID 34771453, 2021). "Selective inhibition of SphK1 by VPC96091 reduced epidermal growth factor (EGF) driven S1P levels and increased Akt/ERK phosphorylation in human leukemia U937 cells and mice model." (PMID 34737701, 2021). "BMSCs can protect leukemia cells against chemotherapy drugs through various cytokines or growth factors (e.g., PDGF, VEGF, EGF, SCF, etc.)or cell-cell surface contact (e.g., SDF1/CXCR4, VLA4/VCAM1, CD44/E-selectin, etc.)." (PMID 34307365, 2021). "Examples include the inhibition of the epidermal growth-factor (EGF)receptors, over-expressed in many solid tumors, and inhibition of Jak2 orBcr-Abl in myeloproliferative disease and leukemia." (PMID 22969412, 2012). "The Weiss group used 20 ng/ml EGF, 20 ng/ml bFGF, and 2 μg/ml heparan sulfate without leukemia inhibitory factor." (PMID 32102678, 2020).
type 2 diabetes (16 papers, 2015 to 2025). "In chronic conditions requiring biopsy procedures, such as lupus nephritis and type 2 diabetes, low urine EGF concentrations have been associated with histologic kidney damage and accelerated decline of renal function." (PMID 36499745, 2022). "The role of EGF in adipogenesis is well-described with EGF receptor (ErbB1) abundance reduced in insulin resistant women with Type 2 diabetes." (PMID 32265830, 2020). "Urinary secretion of EGF as a marker of tubular mass in a cohort from the Edinburgh Type 2 Diabetes Study was recently demonstrated to predict the decline of renal function independently of traditional risk factors and before the onset of microalbuminuria." (PMID 31388341, 2019). "Recently, we demonstrated that SMSr interacted with the δ isozyme of DG kinase (DGKδ), which is involved in the pathogenesis of type 2 diabetes, obsessive–compulsive disorder, and epidermal growth factor–dependent cell proliferation, via their sterile α motif domains (SAMDs)." (PMID 33621517, 2021). "Future studies are needed to compare the levels of these proteins between patients with type I vs. type II diabetes to differentiate whether type I and type II diabetes have different effects on the expression of ASC, IL-18, CRP, uPA, EGF, and NGAL." (PMID 35355862, 2022).